IPMK (inositol polyphosphate multikinase)
Description:
Inositol phosphate kinase with a broad substrate specificity. Phosphorylates inositol 1,4,5-trisphosphate (Ins(1,4,5)P3) first to inositol 1,3,4,5-tetrakisphosphate and then to inositol 1,3,4,5,6-pentakisphosphate (Ins(1,3,4,5,6)P5). Phosphorylates inositol 1,3,4,6-tetrakisphosphate (Ins(1,3,4,6)P4). Phosphorylates inositol 1,4,5,6-tetrakisphosphate (Ins(1,4,5,6)P4) (By similarity). Phosphorylates glycero-3-phospho-1D-myo-inositol 4,5-bisphosphate to glycero-3-phospho-1D-myo-inositol 3,4,5-trisphosphate. Plays an important role in MLKL-mediated necroptosis via its role in the biosynthesis of inositol pentakisphosphate (InsP5) and inositol hexakisphosphate (InsP6). Binding of these highly phosphorylated inositol phosphates to MLKL mediates the release of an N-terminal auto-inhibitory region, leading to activation of the kinase. Essential for activated phospho-MLKL to oligomerize and localize to the cell membrane during necroptosis. Required for normal embryonic development, probably via its role in the biosynthesis of inositol 1,3,4,5,6-pentakisphosphate (Ins(1,3,4,5,6)P5) and inositol hexakisphosphate (InsP6) (By similarity).
Tractability: Small molecule: a structure with a bound ligand is known; a high-quality ligand is known. PROTAC: ubiquitination databases record sites on it; a small molecule that binds it is known.
Target class: Enzyme; Transferase
Gene: Protein-coding gene on chromosome 10 (58,191,517 to 58,267,959, reverse strand). Ensembl gene ENSG00000151151.
Subcellular location: Nucleus
Subcellular location (Human Protein Atlas): Nucleoplasm; Basal body
Pathways (Reactome):
Metabolism: Synthesis of IPs in the nucleus
Gene Ontology:
Molecular function: flavonoid binding; inositol-1,3,4,5-tetrakisphosphate 6-kinase activity; inositol-1,3,4,6-tetrakisphosphate 5-kinase activity; inositol-1,4,5-trisphosphate 3-kinase activity; protein binding; 1-phosphatidylinositol-4,5-bisphosphate 3-kinase activity; inositol-1,4,5,6-tetrakisphosphate 3-kinase activity; inositol-1,4,5-trisphosphate 6-kinase activity; inositol phosphate kinase activity; kinase activity
Biological process: inositol trisphosphate metabolic process; necroptotic process; inositol phosphate metabolic process; inositol phosphate biosynthetic process; organophosphate metabolic process; phosphatidylinositol metabolic process
Cellular component: nucleoplasm; nucleus; cytoplasm
Genetic constraint (gnomAD): Loss-of-function variants: 8 observed, 24.05 expected, observed/expected ratio (o/e) 0.33, 90% interval 0.19 to 0.6. The upper end of that interval is the gene's LOEUF score, 0.6, which puts it in group 2 of 6, group 1 being the genes least tolerant of losing a copy. Missense variants: 285 observed, 343.26 expected, observed/expected ratio (o/e) 0.83, 90% interval 0.75 to 0.92. Synonymous variants: 138 observed, 135.9 expected, observed/expected ratio (o/e) 1.02, 90% interval 0.88 to 1.17.
Homologues: Orthologues: chimpanzee IPMK (99% identical), macaque IPMK (99% identical), rabbit IPMK (93% identical), dog IPMK (91% identical), guinea pig IPMK (82% identical), rat Ipmk (82% identical), mouse Ipmk (81% identical), tropical clawed frog ipmk (62% identical), pig IPMK (52% identical), zebrafish ipmkb (52% identical), zebrafish ipmka (43% identical), Drosophila melanogaster Ipk2 (27% identical), and 1 more. Paralogues in human: IP6K1 (20% identical), IP6K2 (19% identical), ITPKB (18% identical), IP6K3 (18% identical), ITPKA (18% identical), ITPKC (17% identical).
Diseases named in the same sentence as IPMK in open-access papers:
IPMK is named in the same sentence as 52 diseases in open-access papers, as found by Europe PMC text mining. Sharing a sentence is not in itself a finding about the gene and the disease. The quoted sentences say what the papers report.
Crohn disease (5 papers, 2019 to 2025). A gastrointestinal disorder characterized by chronic inflammation involving all layers of the intestinal wall, noncaseating granulomas affecting the intestinal wall and regional lymph nodes, and transmural fibrosis. "Recently, the identification of single-nucleotide polymorphisms (SNPs) in human IPMK from immune-mediated diseases (e.g., rheumatoid arthritis, psoriasis, and Crohn’s disease) suggests that IPMK contributes to the onset and progression of these diseases." (PMID 36830701, 2023). "SNPs that have statistically significant associations with Crohn disease include rs1819658, located in an enhancer of the IPMK gene (p = 9.0 x 10−17), and rs2790216, located in intron 1 of IPMK (p = 8.0 x 10−9)." (PMID 37216099, 2023). "Differences in IPMK activity may contribute to the risk for Crohn disease, and drugs targeting the PI3k activity of IPMK may have potential as novel treatments for Crohn disease and related conditions." (PMID 37216099, 2023). "Genome-wide association studies previously identified IPMK as a major Crohn’s disease-related gene." (PMID 37216099, 2023). "In our study, the observations of loss of Paneth cells in IPMK-deleted intestine indicates that IPMK is critical for intestinal regeneration and may be linked to Crohn disease." (PMID 37216099, 2023). "Additional AD risk loci, specifically the Human leukocyte antigen (HLA) locus and Inositol Polyphosphate Multikinase (IPMK), have been found to harbor variants that are pleiotropically associated with other immune-related diseases, such as Crohn disease and psoriasis." (PMID 36076238, 2022). "Thus, loss of function of IPMK may drive pathology in Crohn disease and IBD by impairing AKT-mediated Paneth cell integrity." (PMID 37216099, 2023). "IPMK dysfunction has been directly linked to human intestinal diseases, with genome-wide association studies strongly connecting IPMK to inflammatory bowel disease (IBD), which includes Crohn’s disease and ulcerative colitis." (PMID 41008573, 2025).
breast carcinoma (3 papers, 2022 to 2025). "In summary, PIPKIα and IPMK expression is elevated in breast cancer at both the mRNA and protein levels." (PMID 38565949, 2024). "To further study the clinical implication of PIPKIα and IPMK in breast cancer, we first analyzed the expression of PIPKIα and IPMK mRNA using the databases of normal breast (GTEx) and breast cancer (TCGA) tissues." (PMID 38565949, 2024). "We used 6 normal breast and 98 breast tumor (breast cancer stage 2A, 2B, 3A, and 3B/3C) biopsy tissues and stained the tissues with IgG control, anti-PIPKIα, and anti-IPMK antibodies." (PMID 38565949, 2024). "In addition, PIPKIα and IPMK expression was significantly elevated and correlated with CTGF expression in breast cancer clinical samples, making PIPKIα and IPMK promising drug targets in YAP/TAZ-driven breast and other cancers." (PMID 38565949, 2024). "Indeed, depletion of PIPKIα and IPMK attenuated the binding of YAP/TAZ with the TEADs and the expression of target genes in breast cancer cell lines (7 and EV1 and EV2)." (PMID 38565949, 2024). "Furthermore, depletion of PIPKIα and IPMK disrupted the binding of YAP/TAZ with the TEADs, leading to lower expression of YAP/TAZ target genes and reduced cell motility in breast cancer cells." (PMID 38565949, 2024). "The role of necroptosis-related genes in breast cancer, such as FASLG, FLT3, HSPA4, IDH2, IPMK, LEF1, and SLC39A7, has not been extensively studied, and these necroptosis-related genes have been confirmed to regulate the biological processes of necroptosis in various types of tumors." (PMID 36675706, 2022).
HIV-1 infection (3 papers, 2021). The type species of lentivirus and the etiologic agent of acquired immunodeficiency syndrome (AIDS). "IPMK or IPPK KO had a minor effect on HIV-1 infection when cells were dosed with PF74 at concentrations of 1.25 μM or lower." (PMID 34613803, 2021). "Further, IPMK KO resulted in enhanced LCV inhibition of HIV-1 infection in a dose-dependent manner, suggesting that IP5 and IP6 counter the antiviral activity of LCV." (PMID 34613803, 2021). "At these concentrations, HIV-1 infection was more robustly inhibited in IPMK KOVector cell lines versus IPPK KOVector cell lines." (PMID 34613803, 2021). "Relative to MT-4 WTVector cells, IPMK KO subtly decreased HIV-1 infection; however, upon IPMK complementation, a larger fraction of target cells was infected." (PMID 34613803, 2021). "Mallery and coworkers disrupted the IPMK gene in 293T cells and evaluated the consequences for HIV-1 infection." (PMID 34563203, 2021). "Sowd and Aiken further showed that knockout of the IPMK gene resulted in a negligible effect on HIV-1 infection of T cells." (PMID 34563203, 2021). "We also determined whether IP5 promotes to HIV-1 infection of target cells, by challenging the IPMK KO CEM cells with HIV-1." (PMID 33476323, 2021). "A modest increase in the inhibition of HIV-1 infection by the CA-targeting compound BI-2 could be observed in IPMK KO cells at concentrations of >100 μM; however, at this concentration, the specificity of the drug becomes difficult to assess owing to cytotoxicity." (PMID 34613803, 2021). "Independent of cell line tested and relative to complemented controls, IPMK KO and IPPK KO reduced HIV-1 infection by greater than 10-fold upon dosing cells with 0.78 or 1.56 nM LCV, respectively." (PMID 34613803, 2021). "Regardless of CEM clone tested, retroviral complementation increased target cell susceptibility to HIV-1 infection (Flag-IPPK and IPMK-Flag cell lines), though not to the level observed in the original CEM cell line." (PMID 34613803, 2021). "The B6 IPPK KO clone supported a 2-fold increase in infection relative to WT cells, and IPMK KO cells had an insignificant increase, suggesting that IP6 does not play a significant role in initial HIV-1 infection of MT-4 cells." (PMID 33476323, 2021).
Huntington disease (3 papers, 2016 to 2025). Huntington disease (HD) is a rare neurodegenerative disorder of the central nervous system characterized by unwanted choreatic movements, behavioral and psychiatric disturbances and dementia. "Interestingly, a loss of inositol polyphosphate multikinase (IPMK) activity has been reported in the striatum of Huntington’s disease (HD) patients and in several cellular and animal models of the disease." (PMID 33282871, 2020). "Recently, a group has reported that IPMK expression is profoundly reduced in Huntington's disease." (PMID 27563828, 2016).
Insulin resistance (3 papers, 2024 to 2025). Increased resistance towards insulin, that is, diminished effectiveness of insulin in reducing blood glucose levels. "Given that the development of NAFLD/NASH is linked to factors such as insulin resistance, lipid metabolism, oxidative stress, and inflammation, it is conceivable that IPMK may play a role in the development of NAFLD/NASH." (PMID 38338668, 2024). "Our previous studies have shown that the deletion of IPMK reduced the activity of insulin signaling in hepatocytes and exacerbated high fat-induced insulin resistance in mice." (PMID 40141045, 2025). "Future studies should investigate whether IPMK deletion directly impacts Elk-1 activity in skeletal muscle and how this contributes to the metabolic phenotypes observed, including insulin resistance and altered lipid metabolism." (PMID 40141045, 2025).
Alzheimer disease (2 papers, 2021 to 2025). A progressive, neurodegenerative disease characterized by loss of function and death of nerve cells in several areas of the brain leading to loss of cognitive function such as memory and language. "A 2016 study explored the genetic overlap between Alzheimer’s disease (AD) and immune-mediated diseases, revealing a significant association between the SNP rs12570088 at the IPMK locus and neurofibrillary tangle (NFT) pathology in AD." (PMID 41008573, 2025). "Over the past two decades, research utilizing animal models and human mutation analyses has revealed IPMK’s involvement in a wide array of human diseases, including inflammatory disorders, obesity, Alzheimer’s disease, inflammatory bowel disease, and intestinal neuroendocrine tumors." (PMID 41008573, 2025). "Another study investigating the relationship between Late Onset Alzheimer’s Disease (LOAD) and longevity found that certain IPMK SNPs, previously associated with decreased longevity, were protective factors for LOAD." (PMID 41008573, 2025). "Future research investigating the roles of IPMK and HOIPs in Alzheimer’s disease (AD) pathology and the aging brain may open new avenues for understanding and potentially treating this devastating neurodegenerative disorder." (PMID 41008573, 2025).
Arthritis (2 papers, 2021 to 2025). Inflammation of a joint. "Instead, they observed an increase in arthritis scores in IPMK-deficient mice, indicating a potential exacerbation of inflammatory responses in this context." (PMID 41008573, 2025). "To investigate the role of myeloid IPMK in inflammatory arthritis, we induced K/BxN serum-transfer arthritis in wild-type (IpmkWT) or myeloid cell-specific IPMK KO mice (LysM-Cre+Ipmkfl/fl designated as IpmkΔLysM) by injecting serum from K/BxN mice." (PMID 34408810, 2021). "In conclusion, our study demonstrated that myeloid IPMK promotes the resolution of arthritis in a K/BxN serum transfer arthritis model." (PMID 34408810, 2021). "Using myeloid cell-specific IPMK knockout (KO) mice, arthritis was induced via intraperitoneal K/BxN serum injection, after which disease severity was evaluated." (PMID 34408810, 2021). "Both wild-type and IPMK KO mice developed similar RA phenotypes; however, conditional deletion of IPMK in myeloid cells led to elevated arthritis scores during the resolution phase, suggesting that IPMK deficiency in myeloid cells impairs the resolution of inflammation." (PMID 34408810, 2021). "Interestingly, IPMK deletion in myeloid cells delays the resolution of K/BxN serum-transfer induced arthritis without altering the initiation or developmental phase." (PMID 34408810, 2021).
diabetes (2 papers, 2012 to 2025). "Finally, we examined the expression of PIK3R1, TPK1, and IPMK in blood samples from 20 people with diabetes before and after intensive insulin therapy." (PMID 40299682, 2025). "Agents that control IPMK functions may provide novel therapeutics in metabolic syndromes such as obesity and diabetes." (PMID 23050966, 2012). "This suggests that METTL14 might influence insulin signaling transduction to enhance diabetes by regulating the expression of TPK1, IPMK, and PIK3R1." (PMID 40299682, 2025).
epithelial ovarian cancer (2 papers, 2018 to 2020). "The IPMK gene has been shown to be involved in cell cycle arrest and apoptosis in ovarian cancer and the BECN1 gene has been suggested to be a tumor-suppressor gene and its expression levels to be associated with ovarian cancer prognosis." (PMID 30416686, 2018).
inflammatory bowel disease (2 papers, 2023 to 2025). A spectrum of small and large bowel inflammatory diseases of unknown etiology. "Genome-wide association study (GWAS) data from patients with inflammatory bowel disease (IBD) have established IPMK as a putative risk gene." (PMID 37216099, 2023). "Considering that increased gut permeability is an early hallmark of Inflammatory Bowel Disease (IBD), future studies are essential to definitively clarify IPMK’s role in intestinal biology and barrier function." (PMID 41008573, 2025).
metabolic syndrome (2 papers, 2012 to 2025). A cluster of metabolic risk factors for CARDIOVASCULAR DISEASES and TYPE 2 DIABETES MELLITUS. "Thus, our results suggest that IPMK mediates whole-body metabolism by regulating muscle metabolism and may be potentially targeted for the treatment of metabolic syndromes." (PMID 40141045, 2025). "Accordingly, drugs that perturb IPMK signaling actions on major metabolic signaling targets, such as Akt, mTOR, and AMPK, may have therapeutic applications for metabolic syndromes (e.g., obesity, type 2 diabetes) and related eating disorders, such as bulimia and anorexia nervosa." (PMID 23050966, 2012).
osteosarcoma (2 papers, 2023 to 2025). A usually aggressive malignant bone-forming mesenchymal neoplasm, predominantly affecting adolescents and young adults. "In the present study, autophagic flux and western blot analysis demonstrated that knockdown of IPMK decreased autophagy in osteosarcoma cells compared to the ebastine-treated group." (PMID 36632464, 2023). "After infection with the mRFP-GFP-LC3 adenovirus, the numbers of yellow and free red puncta in the si-IPMK+ebastine group were both significantly lower than those in the ebastine group, indicating that autophagosomes and autolysosomes had decreased in the three osteosarcoma cell lines." (PMID 36632464, 2023). "More importantly, we found that IPMK interacted with AMPK and functioned as a positive regulator of AMPK protein in osteosarcoma cells." (PMID 36632464, 2023). "We provide experimental evidence demonstrating that ebastine has antitumor activity in osteosarcoma and promotes autophagy by activating the AMPK/ULK1 signaling pathway, which is IPMK dependent." (PMID 36632464, 2023).
renal carcinoma (2 papers, 2019 to 2023). A carcinoma arising from the epithelium of the renal parenchyma or the renal pelvis. "Depletion of IPMK in 786-0 (a renal cancer cell lines) substantially reduced AKT Thr308 phosphorylation." (PMID 37216099, 2023). "Using small hairpinRNA (shRNA), we stably knocked down IPMK in 786-0 renal cancer cells." (PMID 30840891, 2019).
age-related macular degeneration (1 paper, 2025). Age-related loss of vision in the central portion of the retina (macula), secondary to retinal degeneration. "Additionally, disease-relevant connections have been identified: in both mouse models and patient tissues of age-related macular degeneration (AMD), reduced levels of IPMK result in impaired HDAC3 activation, disrupted gene regulation, and increased proteostatic stress." (PMID 41008573, 2025).
breast tumor (1 paper, 2024). "In each tissue, the breast tumor was histologically located by H&E staining, and the staining of PIPKIα and IPMK in the tumor area was scored by a 0, 1, 2, and 3 scale." (PMID 38565949, 2024). "We found that ~76% (75/98) and ~71% (69/97) of breast tumor tissues show moderate or strong staining with antibodies to PIPKIα and IPMK, respectively." (PMID 38565949, 2024). "Compared to normal tissue, the levels of PIPKIα and IPMK mRNA were significantly elevated in breast tumor tissues (Fig. EV4D)." (PMID 38565949, 2024).
colitis (1 paper, 2024). Inflammation of the colon. "Inositol polyphosphate multikinase (IPMK) crucially regulates the homeostasis of tuft cells and indirectly affects the onset and progression of colitis." (PMID 38886630, 2024).
colon cancer (1 paper, 2025). "Additionally, since human data suggest a role for IPMK in intestinal tumors, it would be valuable to investigate the effects of IPMK mutations, loss, or gain of function in both human tissue and murine models of colon cancer, which is more prevalent." (PMID 41008573, 2025).
glioblastoma (1 paper, 2025). The most malignant astrocytic tumor (WHO grade IV). "The compounds presented here will form the basis of futureefforts to develop IPMK inhibitors with the potential for clinicalapplications, particularly in human glioblastoma." (PMID 40709844, 2025). "Here, we report a novel series of highly potent IPMK inhibitors.The first-generation IPMK inhibitor 1 (UNC7437) decreasedcellular proliferation and tritiated inositol phosphate levels inmetabolically labeled human U251-MG glioblastoma cells." (PMID 40709844, 2025). "Our data suggest thatchemical inhibition of IPMK can reveal novel metabolic profiles inhuman glioblastoma cells that were not previously observed using geneticapproaches." (PMID 40709844, 2025). "It is, therefore, tempting to speculate that chemical inhibitorsof IPMK may be capable of uniquely targeting PTEN-negative glioblastoma,particularly in patients who have not responded well to therapiesthat decrease AKT phosphorylation." (PMID 40709844, 2025).